NPC1 (NPC intracellular cholesterol transporter 1)
Diseases named in the same sentence as NPC1 in open-access papers (continued):
Sharing a sentence is not in itself a finding about the gene and the disease.
Niemann-Pick disease type A (2 papers, 2023 to 2025). Niemann-Pick disease type A is a very severe subtype of Niemann-Pick disease, an autosomal recessive lysosomal disease, and is characterized clinically by onset in infancy or early childhood with failure to thrive, hepatosplenomegaly, and rapidly progressive neurodegenerative disorders. "To begin to assess the contribution of these secondary lipid accumulations to the hypomyelination phenotype in Npc1−/− mice, we evaluated myelination in a mouse model of Niemann–Pick type A disease." (PMID 37407594, 2023).
prostate carcinoma (2 papers, 2021 to 2025). A carcinoma that arises from epithelial cells of the prostate gland. "Further multivariate Cox regression analysis was performed to select 6-gene prognostic signature (FADD, GABARAPL2, MYC, RAB24, RUBCN, and NPC1) and calculated the risk score of the prostate cancer patients." (PMID 33402116, 2021). "Utilizing the Oncomine database, we observed a pronounced upregulation of NPC1 in the majority of cancer types examined, including cervical, kidney, liver, lymphoma, pancreatic, and prostate cancers." (PMID 40881173, 2025).
reovirus infection (2 papers, 2022 to 2023). "Using genome-wide CRISPR/Cas9 and short interfering RNA (siRNA)-based cell-survival screens, researchers found that NPC1 was a necessary host component for reovirus infection." (PMID 38098077, 2023). "We characterized NPC1 KO cells for the capacity to support each step of the reovirus entry pathway to define the function of NPC1 in reovirus infection." (PMID 35263388, 2022). "In this study, we identified NPC1 as a putative host factor required for reovirus infection using genome-wide CRISPR/Cas9 and siRNA-based cell-survival screens." (PMID 35263388, 2022). "Together, these results suggest that NPC1 is required for reovirus infection and functions at a step in the infectious cycle that differs between virions and ISVPs." (PMID 35263388, 2022). "In this study, we used CRISPR and RNA interference screens to discover that Niemann Pick C1 (NPC1), an endolysosomal transmembrane protein that mediates cholesterol egress from late endosomes for redistribution to cellular membranes, is required for reovirus infection." (PMID 35263388, 2022). "We used CRISPR/Cas9 gene-targeted HBMECs lacking NPC1 expression to study the function of NPC1 in reovirus infection." (PMID 35263388, 2022). "We found that genetic ablation of NPC1 in human brain microvascular endothelial cells (HBMECs) diminishes reovirus infection by virions but not by ISVPs, suggesting that NPC1 is required for replication steps that differ between virions and ISVPs." (PMID 35263388, 2022). "We found that reovirus infection is significantly impaired in cells lacking NPC1, but infection is restored by treatment of cells with hydroxypropyl-β-cyclodextrin, which binds and solubilizes cholesterol." (PMID 35263388, 2022).
triple-negative breast carcinoma (2 papers, 2022 to 2025). An invasive breast carcinoma which is negative for expression of estrogen receptor (ER), progesterone receptor (PR), and human epidermal growth factor receptor 2 (HER2). "Studies have shown that NPC1 inhibition in triple-negative breast cancer reduces cellular proliferation and alters mitochondrial activity, among other effects." (PMID 40881173, 2025). "As a method of identifying novel therapeutic targets in this disease subtype, we utilize a microRNA that reverses the Epithelial-to-Mesenchymal Transition, which reveals Niemann-Pick C1 (NPC1) as a gene highly expressed in triple negative breast cancer." (PMID 35884604, 2022).
acid sphingomyelinase deficiency (1 paper, 2023). An autosomal recessive lysosomal disease caused by biallelic loss of function variants in the SMPD1 gene. "It is interesting to note that there are some similarities that exist between NPC1/2 and NPC A/B, which is also known as acid sphingomyelinase deficiency (ASMD) that affects ~1 in 250,000." (PMID 37189685, 2023).
angiomyolipoma (1 paper, 2021). A neoplasm with perivascular epithelioid cell differentiation often associated with tuberous sclerosis. "Interestingly, NPC1 is also enriched in renal lesions from TSC patients (angiomyolipomas and RCCs) compared with adjacent normal kidney." (PMID 34253722, 2021).
aspiration pneumonia (1 paper, 2020). "NPC1 patients usually die following the neurological disease progression, leading to respiratory complications such as aspiration pneumonia and respiratory failure." (PMID 32709131, 2020).
astrocytoma (1 paper, 2009). "In cultured human astrocytoma cells (CCF-STTG1), both haloperidol and clozapine significantly up-regulated ApoE, NPC1 and NPC2 at 24 hours of incubation (n = 3)." (PMID 19715613, 2009).
Atrophy (1 paper, 2016). Any weakening or degeneration, especially through lack of use. "In addition, it was reported that CtsB/L KO mice show progressive neuronal loss and substantial brain atrophy, similar as NPC1 deficient mice." (PMID 27902765, 2016).
Brain atrophy (1 paper, 2017). Partial or complete wasting (loss) of brain tissue that was once present. "Variability in clinical reports of MRI-visible brain atrophy is likely due to differences in disease severity associated with the over 240 separate mutations of NPC1 which are currently known to cause disease." (PMID 28542381, 2017). "The current study utilized high-resolution in vivo 3D MRI in combination with atlas-based segmentation to investigate whole brain and region specific brain atrophy in the Npc1-/- mouse model of NPC1 disease." (PMID 28542381, 2017). "The ability to measure in vivo neurodegeneration evidenced by brain atrophy provides an additional means to monitor disease status and could prove useful in future studies of treatments in the Npc1-/- mouse model of NPC1 disease." (PMID 28542381, 2017).
cerebellar disorder (1 paper, 2015). Diseases that affect the structure or function of the cerebellum. "This also offers the option to analyze and separate proteins to determine factors which show an importance in the protein expression, for other major cerebellar disorders like NPC1 for example, in future studies." (PMID 26370973, 2015).
Cerebral atrophy (1 paper, 2019). Atrophy (wasting, decrease in size of cells or tissue) affecting the cerebrum. "Like NPC1 patients, NPC1 deficient (Npc1−/−) mice develop progressive neurodegeneration characterised by cerebral atrophy, hypomyelination and degeneration of cerebellar Purkinje cells." (PMID 30847690, 2019).
cervical cancer (1 paper, 2022). A primary or metastatic malignant neoplasm involving the cervix. "In particular, the NDRG1, HK2, PLOD2, EGLN3, and NPC1 genes showed a higher expression in tumors than in normal tissues, and cervical cancer patients overexpressing these genes had a poor prognosis compared with those who showed low expression levels of these genes." (PMID 36551576, 2022).
childhood dementias (1 paper, 2020). "The impact of disrupted cholesterol trafficking by NPC1 deficiency in neural cells development is unknown, leading to a poor understanding of the origin of and preclinical mechanisms that lead to childhood dementia." (PMID 32611604, 2020).
cholestatic jaundice (1 paper, 2014). "This was an infant with cholestatic jaundice without confirmed diagnosis, who was later excluded as NP-C or a heterozygote of NPC1/NPC2 gene by molecular analysis." (PMID 24915861, 2014).
cyst (1 paper, 2024). A sac-like closed membranous structure that may be empty or contain fluid or amorphous material. "Further analyses are needed to evaluate whether the blockage of cholesterol redistribution via NPC1 inhibition may represent a potential therapeutical target not only against cyst-forming-but also against non-cyst-forming-coccidian parasites." (PMID 39183751, 2024).
Dyskinesia (1 paper, 2024). A movement disorder which consists of effects including diminished voluntary movements and the presence of involuntary movements. "This case enriches the types of NPC1 gene mutations, suggesting that we should actively learn the medical and family histories and perform a detailed physical examination in patients with prolonged neonatal jaundice, unexplained hepatosplenomegaly, dyskinesia and neuropsychiatric symptoms." (PMID 38291356, 2024).
Epileptic encephalopathy (1 paper, 2026). A condition in which epileptiform abnormalities are believed to contribute to the progressive disturbance in cerebral function.
gallstones (1 paper, 2022). Solid crystalline precipitates in the biliary tract, usually formed in the gallbladder, resulting in the condition of cholelithiasis. "These loci are located in seven different genes, including SLC4A5, MUC4, FTO, NPC1 and FXYD2 genes that may increase the risk of gallstone in the Tibetan population, while CFTR and ADCY2 genes that reduce the risk of gallstone in the Tibetan population." (PMID 35651949, 2022). "Also, the mouse animal model showed that NPC1 gene regulates the formation of gallstones by controlling cholesterol in the liver, suggesting that the expression of NPC1 gene may be related to the formation of cholesterol stones." (PMID 35651949, 2022).
gestational diabetes (1 paper, 2015). Carbohydrate intolerance first diagnosed during pregnancy. "In summary, this is the first transferability study to investigate common NPC1 polymorphisms in a multiethnic population and demonstrate a differential association with increased risk for maternal prepregnancy overweight and gestational diabetes." (PMID 26120596, 2015).
Glucose intolerance (1 paper, 2014). Glucose intolerance (GI) can be defined as dysglycemia that comprises both prediabetes and diabetes. "Further, mice heterozygous for NPC1 have increased susceptibility to weight gain and display abnormal metabolic characteristics such as hyperinsulinemia and glucose intolerance, and this impairment in glucose tolerance is independent of body weight." (PMID 24752197, 2014).
hearing loss (1 paper, 2022). "In this study, we state a novel molecular mechanism of NPCD in causing genetic hearing loss, that is, NPC1 deficiency induces ferroptosis in auditory cells through an autophagy-dependent ferritinophagy manner." (PMID 35936782, 2022).
hemorrhagic fever (1 paper, 2024). An infectious disease caused by certain viruses or bacteria that can damage the walls of tiny blood vessels, making them leak, and can hamper the blood's ability to clot and cause severe, life-threatening illness. "Instead, it resembles molecules such as NPC1 and LAMP1—so called intracellular receptors for hemorrhagic fever viruses—which promote viral fusion with endolysosomal membranes, but do not mediate virus attachment to cells." (PMID 38359079, 2024).
hepatitis A (1 paper, 2024). "Further, the lipid receptors hepatitis A virus cellular receptor 1 (HAVCR1) and NPC intracellular cholesterol transporter 1 (NPC1) were found to be required for endosomal fusion and cargo delivery, and HAVCR1 was shown to serve as a receptor for hepatitis A EVs and mediate infection." (PMID 39811728, 2024).
Hyperinsulinemia (1 paper, 2013). An increased concentration of insulin in the blood. "Very recently, Jelinek and colleagues have reported that Npc1 haploinsufficiency developed abnormal metabolic features (including hyperinsulinemia) and increased susceptibility to weight gain in mice." (PMID 23375129, 2013).
immune deficiency (1 paper, 2024). "Interestingly, the pair NPC1 (AAEL009531) and NPC2 (AAEL001650) is suggested to function together and negatively affect the immune deficiency immune signalling pathway in mosquitos infected with dengue virus serotype 2." (PMID 38338961, 2024).
iron metabolic disorders (1 paper, 2022). "Our results indicated that autophagy was involved in NPC1 deficiency–induced iron metabolic disorders." (PMID 35936782, 2022).
Lassa virus infection (1 paper, 2022). "Importantly, whereas abrogation of one molecule (NPC1/Lamp1) completely inhibits EBOV or Lassa virus infection, ASFV infection was only partially inhibited and, in view of our results, could involve the interaction of several endosomal proteins." (PMID 35081156, 2022).
Lewy body diseases (1 paper, 2021). "However, given the young age of cases manifesting Lewy bodies, much younger than the age at which incidental Lewy body disease typically occurs, one could suggest an association between NPC1 mutations and α-synuclein aggregation." (PMID 34056672, 2021). "Taken together, these findings suggest that whilst NPC1 is not a risk factor for idiopathic Lewy body diseases, there is evidence to suggest dysregulation of lipid species associated with Niemann–Pick Type C1." (PMID 34056672, 2021).
lipid metabolism disorder (1 paper, 2024). "Compared with the Control group, the mRNA expression of Srebf2, Scap, Hmgcr, Soat1, Npc1, Snai3, Twist1, Itgav, Vegfc, and Tgfbr1 has higher expression in model group, indicating that there is lipid metabolism disorder in model mice." (PMID 38724499, 2024).
lymphangioleiomyomatosis (1 paper, 2021). A multifocal neoplasm with perivascular epithelioid cell differentiation affecting almost exclusively females of child-bearing age. "We found that TFEB is predominantly nuclear in Human Melanoma Black-45 (HMB45) and NPC1-positive lymphangioleiomyomatosis (LAM) nodules, the pulmonary manifestation of TSC37." (PMID 34253722, 2021).
metachromatic leukodystrophy (1 paper, 2025). A rare lysosomal storage disorder characterized by intralysosomal accumulation of sulfatides in various tissues, leading to progressive deterioration of motor and neurocognitive function. "The secondary NEU1 deficiency occurred in the brains of all analyzed mouse models of neurological MPS (MPS I, II, IIIA, IIIB, IIIC) but not in the models of other LSDs (metachromatic leukodystrophy, ML IV, Tay-Sachs, or NPC1)." (PMID 40540388, 2025).
mitochondrial DNA depletion syndrome (1 paper, 2022). The mitochondrial DNA (mtDNA) depletion syndrome (MDS) is a clinically heterogeneous group of mitochondrial disorders characterized by a reduction of the mtDNA copy number in affected tissues without mutations or rearrangements in the mtDNA. "Three of the detected genes, POLG, NPC1, and CFTR, were not included in the old 18-gene panel and patients harboring variants in them were molecular diagnosed with mitochondrial DNA depletion syndrome, NPC and CF, respectively." (PMID 37168916, 2022).
multiple myeloma (1 paper, 2025). "Notably, U18666A, an NPC1 inhibitor, significantly enhanced the therapeutic efficacy of conventional chemotherapy in established multiple myeloma (MM) and solid tumors, highlighting the potential for NPC1 inhibitors as promising novel chemotherapeutic agents." (PMID 41013744, 2025).
neuropathy (1 paper, 2011). A disorder affecting the nervous system that manifests with pain, tingling, numbness, and/or muscle weakness. "Most striking are data demonstrating that the lipid chelator 2-hydroxypropyl-β-cyclodextrin (CD) partially can replace the function of NPC1 and NPC2 proteins, diminishes neuropathy, delays motor deficits, and increase median survival in both NPC1−/− and NPC2−/− mice." (PMID 22073306, 2011).
non-alcoholic fatty liver disease (1 paper, 2018). "Additionally, the excessive accumulation of lipids in Npc1−/− mice was associated with hepatocellular necrosis and enhanced hepatic inflammatory activity, a widely known phenomenon of non-alcoholic fatty liver disease." (PMID 29587349, 2018).
osteoarthritis (1 paper, 2021). A noninflammatory degenerative joint disease occurring chiefly in older persons, characterized by degeneration of the articular cartilage, hypertrophy of bone at the margins and changes in the synovial membrane. "We found strong evidence for co-localisation of five osteoarthritis signals with cartilage molQTLs for ALDH1A2, NPC1, SMAD3, FAM53A and SLC44A2." (PMID 33637762, 2021).
osteoporosis (1 paper, 2025). A condition of reduced bone mass, with decreased cortical thickness and a decrease in the number and size of the trabeculae of cancellous bone (but normal chemical composition), resulting in increased fracture incidence. "Consistently, previous studies have proposed that NPC1 was associated with body weight and adipocyte processes across various animals and TMEM241 was associated with bone degeneration and osteoporosis." (PMID 40330097, 2025).
placental insufficiency (1 paper, 2019). Failure of the placenta to deliver an adequate supply of nutrients and oxygen to the fetus. "One possible cause for this would be placental insufficiency, supported by the presentation of placentomegaly in multiple fetal NPC1 patients along with a report describing a fetal-onset NPC1 patient with abnormal placental pathology, including foamy cells in the villous stroma." (PMID 31861571, 2019).
protein misfolding diseases (1 paper, 2014). "In order to determine whether the MSR observed in CF is a general phenomenon associated with protein misfolding diseases, we monitored the HSR activation state in models of AATD, NPC1, and AD." (PMID 25406061, 2014).
pulmonary alveolar proteinosis (1 paper, 2020). A rare lung disorder characterized by the filling of the pulmonary alveoli with proteinaceous material which stains positive with periodic acid-Schiff stain. "It is thought to be caused by the lung infiltration by foamy macrophages and is associated with pulmonary alveolar proteinosis, unlike NPC1 patients in whom respiratory complications are typically due to recurrent aspirations and infections." (PMID 32709131, 2020).
squamous carcinoma (1 paper, 2022). "This is consistent with a recent study demonstrating that NPC1 inhibition reduces migration and invasion in Chinese hamster ovarian and A431 squamous carcinoma cell lines." (PMID 35884604, 2022).
testicular tumors (1 paper, 2025). "Conversely, in cancers like thyroid or testicular tumors, cholesterol metabolism may be less dominant, leading to NPC1 downregulation." (PMID 40881173, 2025).
Thrombocytosis (1 paper, 2020). Increased numbers of platelets in the peripheral blood. "As anticipated, platelet count levels towards the lower end of the normal range was observed in our clinical hematological studies in NPC1 disease patients; however, thrombocytosis was observed in the Npc1−/− mice." (PMID 33204596, 2020).